TERT (telomerase reverse transcriptase)
Diseases named in the same sentence as TERT in open-access papers (continued):
Sharing a sentence is not in itself a finding about the gene and the disease.
tumor (continued). "As an example of this, despite the fact that 2XSB cells and their parent tumor had a C250T (− 146 bp) mutation in the core promoter of the TERT gene, our RNA-Seq dataset showed very low TERT mRNA expression." (PMID 33707600, 2021). "In summary, examining a cohort of de novo HGMs following adjuvant RT, we find TERT alteration to be strongly associated with tumor progression and poor outcome of HGM patients included in this study." (PMID 34778063, 2021). "To unravel these different theories of UBC development we tested if TERT promoter mutations occur early in proposed pre-stage tissues associated with the tumor and play a role during tumorigenesis." (PMID 33562516, 2021). "Thereafter, TERT promoter mutations were found to be one of the most frequently mutated genomic regions in several tumor tissues." (PMID 34395278, 2021). "Despite the presence of the TERT promoter mutation, TERT transcripts were difficult to detect in 2XSB cells and the parent tumor." (PMID 33707600, 2021). "When analyzed by tumor characteristics, TERT promoter mutations tended to be more frequent in single (37/109, 33.9%) versus multiple (20/92, 21.7%) HCC (p = 0.056)." (PMID 33946181, 2021). "Direct promoter activation can lead to increased TERT activity in tumor cells, and two common promoter mutations (-124 and -146 bp upstream of the TERT start site) have been associated with increased telomerase activity." (PMID 34201898, 2021). "Mutations of the TERT promoter in BC resulted in increased TERT mRNA levels and increased tumor invasiveness." (PMID 33938397, 2021). "Overexpression of the TERT gene then increases tumor cell telomere stability and is linked to cell overdevelopment and malignant transformation." (PMID 34070093, 2021). "We identified SNVs in the exo-DNA that were not present in tumor DNA at onset of disease, in particular mutations of ALK, ATRX, NF1, and TERT genes, probably coming from other tumor sites." (PMID 33915956, 2021). "After reviewing the patients’ files, it thus became clear that TERT promoter-mutated tumor presented with a more aggressive metastatic pattern." (PMID 34108637, 2021). "TERT promoter mutation was associated with older age, large tumor size, extrathyroidal extension, advanced T and N stage, and higher recurrence rates according to the American Thyroid Association recurrence risk estimator." (PMID 34070093, 2021). "In our results, the clinicopathological association and patterns of the TERT-telomere network varied substantially with the underlying disease, tumor stage, and differentiation." (PMID 33946181, 2021). "TERT promoter mutations, found in more than 70% of primary GBMs and ODGs, enhances the telomerase activity and tumor growth and is associated with a poor outcome in GBMs." (PMID 33981597, 2021). "Our findings suggest that TERT-alt is associated with tumor progression and poor outcome of newly diagnosed HGM patients after postoperative RT." (PMID 34778063, 2021). "Mutations in the TERT promoter are also associated with tumor aggressiveness and increased recurrence and mortality." (PMID 33562809, 2021). "BRAFV600E-mutated tumours typically demonstrate extrathyroidal extension and are generally of advanced stage with TERT promoter mutation with evidence of lymph node and distant metastases." (PMID 34062862, 2021). "Together with tumor extent, TERT promoter mutations (hazard ratio (HR) = 4.24, 95% CI: 1.75–10.26, p = 0.001) were identified as an independent factor for OS after hepatectomy." (PMID 33946181, 2021). "We found that a certain subset of tumors among TERT promoter-mutated PTCs were prone to anaplastic transformation during tumor development." (PMID 33761111, 2021).
tumor (continued). "In contrast to the tumor, tumor associated normal urothelium was a different TERT promoter mutation compared to the MIBC." (PMID 33562516, 2021). "Genetic analysis studies found the prevalence of clonal TERT promoter mutations in 61–73% of ATCs and 40% of PDTCs, lending further credence to its importance in tumour progression." (PMID 34062862, 2021). "Activating TERT gene mutations in the upstream promoter allows overexpression of this enzyme and is responsible for immortalization of tumor cells in many cancers." (PMID 34778063, 2021). "The TERT promoter mutation at −124 C > T was found in 45% of all patients and was significantly associated (p > 0,001) with higher tumor grade, shorter metastasis-free survival, and disease-specific survival." (PMID 34108637, 2021). "The risk of tumor development for patients over 60 years of age raised with increasing TERT mRNA levels [HR and 95%C.I." (PMID 34746013, 2021). "A low tumor mutation burden (4–7 muts/Mb) characterized most of the testicular LCT except the peculiar metastatic case with a B4GALT5:TERT fusion and TOP1 and CCND3 amplifications that exhibited 11 muts/Mb." (PMID 33741265, 2021). "In keeping with our previous findings, we found that the mucosa adjacent to tumours harbouring TERT promoter mutations had significantly shorter telomeres than those in adjacent mucosa of cancers with unmutated TERT promoter (p=0.017)." (PMID 34858860, 2021). "We also identified a rare somatic promotor mutation in the TERT gene associated with the tumor progression." (PMID 34940133, 2021). "Forty-five tumours harboured TERT promoter mutations (31.3%), with -124 C>T and -146 C>T accounting for 64.4% and 35.6% of the alterations respectively." (PMID 34858860, 2021). "Strikingly, only TERT mutations were significantly associated with tumor progression (n = 8, adjusted p = 0.031), and all these mutations were present in tumors that progressed after RT." (PMID 34778063, 2021). "It has been shown that TERT promoter mutations confer an aggressive feature to the tumor, and it is likely that even cells with very low allelic fraction mutation for TERT will have replicative advantage." (PMID 33776938, 2021). "TERT promoter mutations have been found to correlate strictly with poor clinicopathological features and bad outcomes of the tumor." (PMID 33572167, 2021). "The observation that TERT promoter mutations occur early during liver carcinogenesis highlights the importance of telomerase activity for tumor cell survival." (PMID 32722302, 2020). "In malignant tumours, TERT mRNA increased expression was associated with older age and larger tumours." (PMID 32659948, 2020). "In tumor grade analysis, the proportion of patients with TERT promoter mutations was higher in low-grade UTUC than that in high-grade ones, which was in agreement with the results of the previous UTUC cohort studies." (PMID 33634022, 2020). "These tumor genetic studies demonstrate that TERT promoter mutation is one of the earliest recurrent somatic genetic alterations during the transformation sequence from liver cirrhosis to HCC." (PMID 33457451, 2020).
tumor (continued). "The tumors were subtyped by gene expression profiling and analyzed for hotspot mutations in FGFR3, PIK3CA and TERT, the most frequent early driver mutations in this tumor type." (PMID 31609466, 2020). "We identified a BRAF(V600E) mutation and a TERT promoter mutation in the PF49 tumor cells and found that these mutations were already present in the primary PTC." (PMID 32591993, 2020). "The SFRP1 methylation status was significantly associated with the gender, age at diagnosis, tumor type, differentiation, extrahepatic growth, resection margin and telomerase reverse transcriptase (TERT) mutations." (PMID 32189106, 2020). "In the context of GBM, Lee and colleagues demonstrated that all the IDH-wild type GBM patients with driver mutations in tumor-free SVZ tissue also presented mutations in the TERT promoter in this tissue." (PMID 33330101, 2020). "In univariable analysis, TERT promoter mutation C250T was significantly associated with increased tumor growth (+ 52.4 mm/year), while MGMT promoter methylation was significantly associated with decreased tumor growth (-37.4 mm/year)." (PMID 32388499, 2020). "TERT promoter mutations were also associated with adverse outcomes including tumor persistence/recurrence (OR, 4.97; 95% CI, 3.78–6.53; P < 0.05) and disease-specific mortality (OR, 8.29; 95% CI, 5.57–12.34; P < 0.05)." (PMID 31655978, 2020). "Integrations at the TERT promoter were associated with high telomerase expression evidently activating this tumor-driving process." (PMID 32025001, 2020). "The same TERT mutation present in tumors 2–3 remained present in the progression tumor, but the inferred ERBB2 amplification status changed." (PMID 31609466, 2020). "GRNVAC1 is a DC-based tumor vaccine and generated through the transfection of mature DCs with TERT mRNA and lysosomal associated membrane protein 1 (LAMP1)." (PMID 32674474, 2020). "After adjusting for WHO grade, ATRX, Ki67, and MGMT, the IDH1, TERT, and 1p/19q molecular groups were independently associated with tumor growth." (PMID 32388499, 2020). "BRAF, NRAS, and TERT somatic mutations were evaluated in patient’s tumor tissue as part of clinical routine." (PMID 33122747, 2020). "Cell cycle analysis revealed a higher proportion of G2 arrested cells after temozolomide treatment in tumor cells deficient of PRFP19 and TERT compared to equally treated tumor cells transfected with respective control vector." (PMID 32991787, 2020). "In the future, it will be of importance to explore the potential of plasmatic cell-free and tumor DNA (cfDNA and ctDNA) detection of TERT promoter mutations for diagnosing early HCC." (PMID 33297335, 2020). "Cytogenetic study of the tumor cells confirmed GBM IDH1 wild type with TERT mutation and EGFR amplification." (PMID 33391387, 2020). "Somatic mutations of TERT in the promoter region and circulating miR-122 have reported as potential noninvasive biomarkers for neoplastic diseases, including liver cancer." (PMID 32424223, 2020). "Nonetheless, 25% of PCAWG tumours bear at least one putative non-coding driver point mutation, and one third (237 out of 785) affected the TERT promoter (9% of PCAWG tumours)." (PMID 32025007, 2020). "TERT promoter mutations were also associated with adverse outcomes, including tumor persistence/recurrence (OR, 5.30; 95% CI, 4.19–6.71; P < 0.05) and disease-specific mortality (OR, 8.29; 95% CI, 5.76–11.93; P < 0.05)." (PMID 31655978, 2020). "The presence of the TERT promoter mutation indicates the underestimation of the tumor grades when observed in grade II–III diffuse gliomas without IDH mutation." (PMID 33228806, 2020). "We found that TERT was highly expressed in RCC tumor tissues, and elevated TERT expression was associated with poor prognosis for patients." (PMID 33061812, 2020). "In a recent study, 16 HBs were included in a Pan-Cancer cohort of pediatric tumors, with the identification of CTNNB1 and TERT, genes already known to be frequently mutated in this type of tumor." (PMID 32432034, 2020).
tumor (continued). "Mutations in the TERT promoter have been shown to occur in many histological tumor types, making these alterations the most frequent somatic abnormalities detected in cancer so far." (PMID 32839402, 2020). "Our results showed that the tumor purity of the TERT mutation group was higher, indicating lower tumor heterogeneity." (PMID 32810393, 2020). "Telomerase reverse transcriptase (TERT) is a classic tumor-associated antigen overexpressed in majority of tumors." (PMID 32570805, 2020). "For example, only around 50% of PCAWG tumours had sufficient coverage to call a mutation (≥90% power) at the two TERT promoter hotspots, probably because the high GC content of this region causes biased coverage." (PMID 32025007, 2020). "In patients with a recurrence, upstream TERT promoter methylation was also associated with higher tumor stage and the presence of lymph node metastasis." (PMID 32849278, 2020). "Similar to the TERTp mutations, TERT mRNA expression was associated with older age at diagnosis and larger size of tumours and there was a tendency towards association between higher levels of TERT mRNA expression and the presence of vascular invasion." (PMID 32659948, 2020). "Since their discovery in 2013 in melanoma samples, mutations in the promoter region of the TERT gene have been found to be frequent in several tumor types." (PMID 32839402, 2020). "We found a mutation in the telomerase reverse transcriptase (TERT) promotor in 3 (4%) cases, and one of these patients presented with a tumor relapse after 31 months." (PMID 33053798, 2020). "The tumor mutation status of the TERT promoter, including TERT C228T and C250T, is associated with disease recurrence and progression of NMIBC." (PMID 32533903, 2020). "The TERT promoter mutations impart a distinctive tumor environment characterized by epithelial-to-mesenchymal transition (EMT) gene expression signature and MAPK signaling." (PMID 32409749, 2020). "Even though, TERT is overexpressed in the GBM tumor and TERT promoter mutated samples, these two gene expression levels were more associated in the recurrent GBM." (PMID 33317554, 2020). "The TERT C228T mutation was detected in both ≤ pT1 tumor and ≥pT2 tumor in pre-TURBT group 1 at high frequency." (PMID 32509577, 2020). "Univariate analysis of the effect of this mutation on DFS of patients showed that C228T TERT promoter mutation was significantly associated with an increased risk of tumor relapse (HR = 3.372; 95% CI: 1.17–9.73; p = 0.025)." (PMID 32850388, 2020). "TERT mutations and DNA repair pathway alterations were reported in 18% and 14%, respectively, of these tumours." (PMID 31959902, 2020). "TERT mutations positively correlated with a higher tumor mutational burden (TMB) value, neoantigen load, and tumor purity." (PMID 32810393, 2020). "In the grade IV tumor group, the TERT-mutated-1p/19q intact group showed a tendency towards longer survival compared with that of the TERT-wildtype-1p/19q intact group, although the difference was not statistically significant (p = 0.19)." (PMID 33228806, 2020). "This tumor usually presents alterations in mitochondrial DNA (mtDNA), along with other mutations, such as TERT promoter (59%), NRAS (9%) and KRAS (6%) mutations." (PMID 32668761, 2020). "One possibility is that repression of all TERT alleles by DNA methylation is a default tumor suppressing response in all cells post-telomerase activation, but selective pressure ensures the persistence of unmethylated alleles, as suggested by others." (PMID 32468444, 2020). "TERT mutations are also outlined as markers of tumor aggressiveness and poor prognosis in several human cancer types." (PMID 32810393, 2020). "High TERT levels in tumor tissue were consistently associated with worse prognosis: 5-year OS was 69% in patients with TERT levels < 1318 and 44% in those with TERT levels > 1318 (P = 0.009)." (PMID 31772219, 2019).
tumor (continued). "Telomerase reverse transcriptase (TERT) promoter mutation can up‐regulate TERT expression and enhance the tumor invasibility." (PMID 30907072, 2019). "The biology of TERT makes it a compelling candidate gene for factors that influence cancer risk and TERT has been recognized as one of the most common tumor markers." (PMID 31454181, 2019). "Recent reports have suggested that TERT promoter mutations are associated with old age, large tumor size, high-risk classifications, and short event-free survival." (PMID 31321477, 2019). "TERT promoter mutations are on the other hand present at lower fractional abundance and show lower concordance to tumour biopsy (73.3%), both in our and other studies." (PMID 31767937, 2019). "As reported, we analyzed 53 tumor samples in the ACO group of which 8 had a TERT promoter mutation, while 57 samples of the control group were TERT promoter mutation negative (p < 0.002)." (PMID 31242620, 2019). "The tumor was wildtype for both positions C228 and C250 of the TERT promoter, as mutations at these sites have been noted as a reliable prognostic indicator of future recurrences in follicular thyroid carcinoma." (PMID 31699114, 2019). "Applying a targeted next generation sequencing panel the tumor demonstrated an activating TERT promoter mutation, a HRAS G12S mutation as well as a BRAF G466E mutation." (PMID 30809375, 2019). "This lower frequency found in metastatic patients compared with localised ones and in healthy subjects (45%) suggested that tumour progression is associated with a defect of pre-existing anti-TERT CD4+ Th1 immunity." (PMID 31358938, 2019). "The first mutation, c.‐332C > T, was detected in a single tumor case and was only one TERT promoter mutation in MTC group of tumors (1/15)." (PMID 31408918, 2019). "They observed that the spontaneous acquisition of TERT promoter mutations was selected for in blood cells from non-tumor individuals with very short telomere due to germline defects in the TERT protein or other telomerase components." (PMID 31285550, 2019). "In brain tumors, cases with concurrent mutations of BRAF and the TERT promoter have been identified and appear to be associated with an aggressive tumor biology." (PMID 31391125, 2019). "Here, we also discussed the available evidence showing the ability of BETi to disrupt long-range chromatin interaction on mutated TERT promoter such as to inhibit c-Myc and AP-1 transcriptional activities independently from tumor genetic background." (PMID 31200515, 2019). "The largest number of associations with neoplasms has been registered for the TERT gene (22 phenotypes)." (PMID 31695696, 2019). "In fact, of the 6 patients confirmed to harbor TERT promoter mutations as well as another driver mutation in their tumor tissue, TERT‐mutated ctDNA was underrepresented or undetectable in plasma relative to the levels of the other mutation analyzed." (PMID 30312528, 2019). "The presence of a TERT promoter mutation was significantly associated with patient age and tumor size in our FT-UMP cohort, suggesting that this genetic event is most often reserved for large tumors resected in patients ≥55 years of age." (PMID 31561592, 2019). "Alternatively, TERT promoter mutations preferentially occur in tumor cells with longer telomeres or occur before the typical initial oncogenic driver translocation." (PMID 29463038, 2018).